KRTAP1-4 (keratin associated protein 1-4)
Description:
In the hair cortex, hair keratin intermediate filaments are embedded in an interfilamentous matrix, consisting of hair keratin-associated proteins (KRTAP), which are essential for the formation of a rigid and resistant hair shaft through their extensive disulfide bond cross-linking with abundant cysteine residues of hair keratins. The matrix proteins include the high-sulfur and high-glycine-tyrosine keratins.
Synonyms: KAP1.4; KRTAP1.4
Tractability: No criterion of Open Targets' tractability assessment is met for any kind of drug.
Gene: Protein-coding gene on chromosome 17 (41,029,351 to 41,030,195, reverse strand). Ensembl gene ENSG00000204887.
Pathways (Reactome):
Developmental Biology: Keratinization
Gene Ontology:
Cellular component: cytosol; keratin filament
Genetic constraint (gnomAD): Loss-of-function variants: 6 observed, 8.91 expected, observed/expected ratio (o/e) 0.67, 90% interval 0.37 to 1.33. That is too few expected variants to judge how well the gene tolerates losing a copy. Missense variants: 157 observed, 150.55 expected, observed/expected ratio (o/e) 1.04, 90% interval 0.92 to 1.19. Synonymous variants: 50 observed, 54.87 expected, observed/expected ratio (o/e) 0.91, 90% interval 0.73 to 1.15.
Homologues: Orthologues: chimpanzee KRTAP1-4 (98% identical), macaque KRTAP1-4 (89% identical), mouse Krtap1-5 (55% identical), rat Krtap1-5 (53% identical). Paralogues in human: KRTAP1-1 (91% identical), KRTAP1-3 (91% identical), KRTAP1-5 (85% identical), KRTAP4-12 (47% identical), KRTAP4-3 (46% identical), KRTAP4-6 (46% identical), KRTAP4-11 (44% identical), KRTAP4-9 (42% identical), KRTAP4-4 (41% identical), KRTAP4-5 (40% identical), KRTAP4-7 (39% identical), KRTAP4-8 (38% identical), and 35 more.